TNF (tumor necrosis factor)
Diseases named in the same sentence as TNF in open-access papers (continued):
Sharing a sentence is not in itself a finding about the gene and the disease.
prostate carcinoma (continued). "The top 20 most enriched pathways included the IL-17 signaling pathway, prostate cancer, bladder cancer, TNF signaling pathway, and endocrine resistance." (PMID 35069766, 2022). "Combined with our previous studies, our findings suggest a comprehensive role for TNF signaling in ADT-induced regression of prostate cancer." (PMID 36551505, 2022). "In support of this, JAG1, a member of the TNFα signaling via NFĸB hallmark, was enriched in ICC/IDC compared to lower Gleason patterns, other Gleason pattern 4 histological subtypes of prostate cancer, and benign prostate luminal epithelial cells." (PMID 36229464, 2022). "Although castration-induced TNF signaling directly triggers epithelial cell apoptotic death in prostate cancers, there is substantial evidence that androgen withdrawal also affects the prostate tumor microvasculature." (PMID 36551505, 2022). "This is also the reason for the sensitivity difference between normal human prostate epithelial cells and prostate cancer cells to TNF-α-induced biological responses." (PMID 36293141, 2022). "TNF signaling has been described as pro-tumorigenic in AR-low prostate cancer, and we confirmed that TNF activity was inversely associated with AR activity in human patients." (PMID 36511483, 2022). "TNF-α-secreting neutrophils have previously been shown to mediate the antitumor efficacy of an oncolytic poliovirus in the xenograft models of breast and prostate cancers." (PMID 36139433, 2022). "We found a significant inverse correlation between TNF and AR activity in human patients, validating our finding that TNF signaling is induced in prostate cancer upon castration." (PMID 36511483, 2022). "To further confirm the inhibition effect of Lycorine on the activation of NF-κB, we determined the effect of Lycorine on TNF-α induced signaling transduction of the NF-κB pathway in prostate cancer cells DU145 and PC3." (PMID 36046655, 2022). "Other line of evidence revealed that capsaicin can inhibit nuclear factor-kappa aka NF-κ activation along with tumor necrosis factor-alpha aka TNF-α in prostate cancer cells." (PMID 36234927, 2022). "In a recent study, Jiang et.al proved lycopene suppressed the inflammatory response by downregulating IL1, IL6, IL8, and TNF-α expression in prostate cancer." (PMID 34055003, 2021). "Sixty-five overlapping targets were closely related to the relevant pathways of prostate cancer (hsa05215), C-type lectin receptor signaling pathway (hsa04625), TNF signaling pathway (hsa04668) and endocrine resistance (hsa01522)." (PMID 33995019, 2021). "Conjugation of LTF to 3-diaminobutyric polypropylenimine dendrimer carrying plasmids encoding for TNFα, TRAIL, or IL-12 improved its transfection and therapeutic efficacy in prostate cancer cells." (PMID 33406760, 2021). "For example, PKCδ promotes the secretion of autocrine factors from prostate cancer cells that bind tumor necrosis factor (TNFα) and TRAIL receptors to stimulate extrinsic apoptosis." (PMID 33430006, 2021). "They found that hsa_circ_0001165 regulated TNF (tumor necrosis factor) expression through miR-187-3p to induce EMT in prostate cancer cells." (PMID 33717646, 2021). "Other inflammatory cytokines with demonstrated reduction after ADT in prostate cancer patients include IL-1β, IL-2, tumor necrosis factor (TNF)-α, and interferon (IFN)-γ." (PMID 34926085, 2021). "On the other hand, elevated pre-diagnostic concentrations of TNFα and its soluble receptors and the activation of TNFα-related pathways have been related to higher risk and poorer survival in endometrial cancer, prostate cancer where could induce a shift to an untreatable phenotype." (PMID 33540543, 2021). "We provide evidence of immunomodulatory intervention of MGF-AuNPs in prostate cancers through observations of enhanced levels of anti-tumor cytokines (IL-12 and TNF-α) with concomitant reductions in the levels of pro-tumor cytokines (IL-10 and IL-6)." (PMID 34408231, 2021).
prostate carcinoma (continued). "The anticancer targets of aloe vera were mainly involved in pathways in cancer, prostate cancer, bladder cancer, pancreatic cancer, and non-small-cell lung cancer and the TNF signaling pathway." (PMID 34899953, 2021). "Stimulation of muscle contraction during PRT releases myokines that lower systemic inflammation, with 4–8 weeks of PRT reducing serum IL-6 and TNFα in prostate cancer patients." (PMID 32056047, 2020). "This study identified that elevated serum levels of inflammatory cytokines IL-8, TNF-α, and CCL2 were associated with accelerated progression to castration resistant disease and correlated with poor overall survival in prostate cancer patients." (PMID 33076397, 2020). "TNF-α promotes the migration of prostate cancer cells to the lymph nodes through the induction of CCR7/CCL21 interactions that promote chemotaxis through lymphatic tissues." (PMID 33076397, 2020). "RNA sequencing data shows an upregulation of immunogenic chemokines and cytokines (CXCL, CSF2, IL6, and TNF) in human prostate cancer cells (PC3, PC3M) and Luminex-assayed cytokine response in mice treated with CRC2631." (PMID 33216833, 2020). "TNF-α can be expressed by TAM and neutrophils and treatment with TNF-α results in reduced ferritin expression in prostate cancer cells." (PMID 33679721, 2020). "Studies with metastatic prostate cancer cells also showed an increase in the adhesion to E-selectin and in migration and invasion after cell treatment with TNF-α, which led to an increase of sLex." (PMID 32872308, 2020). "Paracrine application of TNFα is known to induce apoptosis and cell cycle arrest in prostate cancer cells." (PMID 32602581, 2020). "Elevated serum levels of IL-6, IL-8, TNF-α, and CCL2 are associated with accelerated progression and poor prognosis in prostate cancer patients." (PMID 33076397, 2020). "Studies in prostate cancer have demonstrated that the inflammatory NF-κB signaling pathway is constitutively activated, primarily by TNF, and it aids in resistance to apoptosis by inducing expression of anti-apoptotic proteins such as Bcl-xL." (PMID 33076397, 2020). "In prostate cancer cells, TNF-α induces VEGFA expression by activating downstream NF-κb signaling, and promotes endothelial cell angiogenesis." (PMID 32993787, 2020). "Such an action has also been found when prostate cancer cells were treated with tumor necrosis factor-α (TNF-α), in which Cxs-based channels enhance the TNF-α-induced apoptosis." (PMID 31338328, 2019). "Bacillus licheniformis derived biogenic SeNPs are very effective in inducing prostate cancer cell death at a minimum concentration of 2 μg Se/ml through a TNF/IRF1 mediated necroptosis pathway and by AR down-regulation." (PMID 32010628, 2019). "The same results are obtained in DU145 prostate cancer cells where piceatannol inhibited tumor necrosis factor-α (TNF-α)-induced invasion by suppressing MMP-9 activation via the AKT-mediated NF-κB pathway." (PMID 30893846, 2019). "Taken together, our findings provide mechanistic insight into promoting apoptosis in prostate cancer cells by ANO1 inhibition through upregulation of TNF-α signaling." (PMID 29899325, 2018). "Cytokines involved in tumor growth and metastases, interleukin 6 (IL-6) and tumor necrosis factor-α (TNF-α), are also important serum biomarkers with high prognostic value in prostate cancer patients." (PMID 29562686, 2018). "In contrast, activation of other PKC isoforms, such as PKCα and PKCδ, by PMA stimulation of prostate cancer cells rather induces cell death due to autocrine TNF and TRAIL signaling." (PMID 30158439, 2018). "In fact, prostate cancer shares a plenty of pathways with other cancers such as TNF, TGF-beta pathways." (PMID 30027097, 2018). "Suppression of ANO1 upregulates TNF-α expression and activates TNF-α signaling, thus promoting apoptosis in prostate carcinoma." (PMID 29899325, 2018).
prostate carcinoma (continued). "Fas-sensitive PC-3 prostate cancer cells were reported to be more sensitive to TNFα-mediated apoptosis and growth inhibition than Fas-resistant DU145 and LNCaP cells." (PMID 29493296, 2018). "Our findings show that ANO1 expression in prostate cancer cells is negatively correlated with TNF-α signaling upstream to activation of caspase." (PMID 29899325, 2018). "Patients showed decreased overall survival when serum values of both IL-6 and TNF-α are found above the 95th percentile values of healthy controls when compared to prostate cancer patients with values below the cutoff." (PMID 29562686, 2018). "TNFα, an inflammatory cytokine, is well known for its ability to induce apoptosis in a wide variety of cancer cells, including prostate cancer cells." (PMID 29493296, 2018). "Here, we show that silencing or inhibition of endogenous ANO1 inhibits cell growth, induces apoptosis and upregulates TNF-α expression in prostate cancer PC-3 cells." (PMID 29899325, 2018). "Lf-bearing DAB dendriplexes encoding TNFα, TRAIL, and IL-12 therefore hold great potential as a novel approach for the gene therapy of prostate cancer." (PMID 29493296, 2018). "Due to a prospective study showing that TNFα and IL-6 levels correlate with the degree of disease, and PSA progression in prostate cancer patients, TNFα and IL-6 are currently suggested as additional markers that reflect the activity level of this disease." (PMID 29946544, 2018). "Pro-inflammatory markers such as IL-6, IL-8, CRP and TNF-α have shown to be elevated beyond normal levels in both breast and prostate cancer patients experiencing CRF." (PMID 28895922, 2017). "The murine prostate cancer cells (RM-1) mixing with MSCs treated with tumor necrosis factor alpha (TNF-α) and interferon gamma (IFN-γ) or vehicle were subcutaneously injected into C57 mice." (PMID 29268703, 2017). "Artepillin C, a specific bioactive component of BGP, was shown to decrease the activity of NF-κB and potentiate the tumor necrosis factor (TNF)-related apoptosis on LNCaP prostate cancer cells." (PMID 28471399, 2017). "Tumour necrosis factor α (TNFα) is involved in the pathogenesis of prostate cancer, a disease where disturbances in the endocannabinoid system are seen." (PMID 28910408, 2017). "Particular areas for improvement included the following: patients halting DMARDs/anti-TNF therapy during infections, knowledge regarding vaccinations and prostate cancer screening uptake." (PMID 28526972, 2017). "We have previously demonstrated that BA-induced apoptosis in androgen-refractory PC-3 human prostate cancer cells, and in addition sensitizes these cells to TNFα-induced apoptosis through suppression of NF-κB." (PMID 28208611, 2017). "Meantime, IL‐7, IL‐8, and TNF‐α were significantly upregulated in patients with prostate cancer compared with patients with BPD and normal control subjects." (PMID 26880719, 2016). "We show that administration of the c-IAP/x-IAP antagonist, AT-IAP, directs a pro-apoptotic response to TNF-α signaling, increasing the sensitivity of prostate cancer cells to RT." (PMID 26799286, 2016). "With regard to NF-κB pathway function in prostate cancer cells, the influence of the canonical NF-κB pathway activation agonists such as TNF and IL-1β is relatively well characterized." (PMID 27975057, 2016). "TNF influence on growth and function of prostate cancer cells in vitro has been well documented and, among other things, it is proven to induce apoptosis in LNCaP cells." (PMID 27975057, 2016). "We have previously shown that apigenin suppresses constitutive and TNFα-induced NF-ĸB activation in human prostate cancer cells, which in turn block the downstream signaling related to cancer progression." (PMID 26435478, 2015). "Our previous studies demonstrate that apigenin suppresses constitutive and TNFα-induced NF-ĸB activation in human prostate cancer cells." (PMID 26435478, 2015).
prostate carcinoma (continued). "In this study, altered β-catenin signaling upon TNFα exposure, and relation to loss of function of the tumor suppressor NKX3.1 was examined in prostate cancer cells." (PMID 25360740, 2014). "Inflammatory cytokines such as IL-6, IL-8 and TNFα have major role in tumor biology and with this notion in mind; production of these cytokines by prostate cancer cell lines was studied at basal level and after stimulation with LPS and LTA." (PMID 24966802, 2014). "PKCɛ also mediated tumor necrosis factor α (TNFα)-induced NF-кB activation by facilitating the assembly of TNF receptor-1 signaling complex in prostate cancer cells." (PMID 24727247, 2014). "Several studies have observed the association between prostate cancer risk and TNF-α promoter polymorphisms, and TNF-α-308G/A and/or TNF-α-238G/A polymorphisms, but the results are controversial." (PMID 24666463, 2014). "Akt/PKB activation has been related to an increased resistance of prostate cancer cells to apoptosis mediated by tumor necrosis factor (TNF)-related apoptosis inducing ligand (TRAIL)/APO-2L." (PMID 24782981, 2014). "Other cell types that were analyzed are prostate cancer lines, where 1α,25(OH)2D3 reduced basal TNFα mRNA expression, or 1α,25(OH)2D3/IL-1β-stimulated synoviocytes, where TNFα mRNA was decreased." (PMID 25071589, 2014). "Therefore, TNF-α polymorphism may be related to prostate cancer risk." (PMID 24666463, 2014). "It seems that maintaining high level of c-FLIP is essential and important in overcoming TNF related apoptosis in the prostate cancer." (PMID 23476140, 2013). "Our finding that MLN cells taken from anti-TNFα-treated H. hepaticus-infected ApcMin/+ lost the prostate cancer promoting effects provides evidence that inflammation enhanced this carcinogenic process." (PMID 23991210, 2013). "TNF-α is produced primarily by immune cells but it is also produced by numerous other cell types, including epithelial cells of human prostate cancer." (PMID 24058525, 2013). "In the present study, the mechanism of α-tomatine in inhibition of TNF-α-induced NF-κB nuclear translocation was investigated by analyzing its effect on phosphorylation and translocation of NF-κB sub-units in prostate cancer PC-3 cells." (PMID 23437404, 2013). "Studies show that introduction of sCLU cDNA into LNCaP prostate cancer cells increases resistance to tumor necrosis factor (TNF) treatment induced apoptosis and oxidative stress." (PMID 23418433, 2013). "Previous reports from our laboratory also established that PKCδ mediates the release of TNFα, a pro-inflammatory cytokine involved in prostate cancer progression." (PMID 23826267, 2013). "Fn14 expression was up-regulated in PC-3 human prostate cancer cells in presence of inflammatory cytokines (TNFα/IFNγ) as well as in presence of bovine fetal serum." (PMID 23077618, 2012). "Our gene array results indicated an increase in TNF and Fas-L in prostate cancer cells, which are ligands for TNFR1 and Fas, respectively, with simvastation treatment." (PMID 22974127, 2012). "Tumours infected with Ad.EGR-TNF respond to radiation with induction of TNF-α expression, and this was investigated in the PC-3 human prostate cancer grown in athymic mice." (PMID 24300371, 2012). "To examine if selected candidate hits can influence TNFα-mediated accumulation of HIF-1α in other cell types we determined HIF-1α nuclear buildup in prostate cancer cell lines." (PMID 22355351, 2012). "Cadmium-mediated XIAP depletion occurs at the post-transcriptional level via an NF-κB-independent, proteasome-mediated mechanism and coincides with an increased sensitivity of prostate cancer cells to TNF-α-mediated apoptosis." (PMID 20618956, 2010). "In this study was investigate IAPs in normal human prostate (NP), benign prostatic hyperplasia (BPH), prostatic intraepithelial neoplasia (PIN) and prostatic carcinoma (PC), and their involvement in apoptosis/proliferation via NF-kB (TNF-α, IL-1) stimulation." (PMID 20078866, 2010).
prostate carcinoma (continued). "In accord with these reports, our data show that cadmium-mediated down-regulation of XIAP coincides with increased sensitivity of PC-3 prostate cancer cells to TNF-α-mediated apoptosis." (PMID 20618956, 2010). "Results of our experiments reveal that pre-treatment with cadmium produces development of apoptosis-resistance in response to concomitant treatment with TNF-α and cadmium in prostate cancer cells." (PMID 20618956, 2010). "In accord, melatonin has been shown to reduce both survivin and Bcl-2 protein levels and subsequently increase the sensitivity of human PC3 prostate cancer cells to TNF-α." (PMID 20920299, 2010). "Further, dNSurR9-C84A rendered prostate cancer cells sensitive to the proapoptotic effects of TNF-α by potentiating the upregulation of caspase-8 activity, suggesting that survivin inhibits the extrinsic pathway of apoptosis." (PMID 20920299, 2010). "FGF19 stimulation of endogenous FGFR4 in TNFα-treated DU145 prostate cancer cells also leads to a decrease in IKKβ activity, concomitant reduction in NFκB nuclear localization, and reduced apoptosis." (PMID 21203561, 2010). "To assess the generality of aCD4 or IFN-γ/TNF-α combination as a radiosensitizer, we tested our approach on the cervical carcinoma cell line Caski, prostate carcinoma cell line DU145 and glioma cell line U373." (PMID 20178622, 2010). "Next we examined the effect of FGF19 treatment on TNFα-induced apoptosis in the DU145 prostate cancer cell line." (PMID 21203561, 2010). "DU145 is an androgen-independent prostate cancer cell line that displays resistance to TNF-α treatment." (PMID 20920299, 2010). "Downregulation of dyskerin by siRNA in prostate cancer cells did not elicit apoptosis by itself or sensitise to induction of apoptosis by TNF-α or tunicamycin, agents chosen because of their relevance to prostate cancer." (PMID 19755982, 2009). "This network reveals the competitive relationship between the two pathways, and indicates the mechanisms of the function alteration of TNF during prostate cancer progression." (PMID 19640296, 2009). "The particular proapoptotic agents were chosen, because death receptor ligands such as TNF-α and endoplasmic reticulum stress, through which tunicamycin acts, are thought to be particularly important in prostate cancer." (PMID 19755982, 2009). "This study provides the first demonstration that midkine expression is induced by certain growth factors and cytokines, particularly TNFα, which offers new insight into understanding how midkine expression is increased in the late stage prostate cancers." (PMID 18275606, 2008). "In prostate cancer cells stimulated with TNF-α, the antibody exhibited strong nuclear staining, as assayed by immunofluorescence, while in nonstimulated cells the staining pattern was mainly cytoplasmic." (PMID 16278667, 2005). "We report elevated serum levels of the cytokines IL-6 and TNF-α in patients with prostate cancer as compared with controls." (PMID 15150588, 2004). "IL-6 and TNF-α, two cytokines with multiple and overlapping biological properties, are involved in prostate cancer development." (PMID 15150588, 2004). "In this study, we measured the serum levels of IL-6 and TNF-α in prostate cancer patients, using a highly sensitive ELISA kit, in an attempt to define their association with clinicopathological features and clinical outcome." (PMID 15150588, 2004). "Moreover, the intake of dairy products is associated with increased IGF-1 levels, promoting proliferation of prostate cancer cells, and an increased secretion of pro-inflammatory cytokines, such as IL-6, IL-1β and tumor necrosis factor (TNF) alpha." (PMID 39954205, 2025). "Additionally, KEGG pathway analysis revealed that AKT1, BCL2, CASP3, and TNF were significantly enriched genes involved in the function of several pathways, including pathways in cancer, Prostate cancer, Chemical carcinogenesis-receptor activation, and others." (PMID 41291087, 2025).